IL1A (interleukin 1 alpha)
Diseases named in the same sentence as IL1A in open-access papers (continued):
Sharing a sentence is not in itself a finding about the gene and the disease.
neuropathy (2 papers, 2019 to 2020). A disorder affecting the nervous system that manifests with pain, tingling, numbness, and/or muscle weakness. "In animals, proinflammatory cytokines IL-1α, IL-1β, and TNF-α are known contributors to the pathogenesis of neuropathy." (PMID 32908447, 2020).
ocular hypertension (2 papers, 2020). Abnormally high intraocular pressure. "Following induction of ocular hypertension, IL-1α, TNF-α, and C1q production was initially driven by CD11b+ CD11c+ cells." (PMID 33147455, 2020).
orchitis (2 papers, 2014 to 2024). Inflammation of one or both testes due to viral or bacterial infections. "Considering that IL1α and TNFα are highly produced in orchitis, the possible role of these cytokines in Sertoli cell proliferation under inflammatory conditions is feasible." (PMID 38666890, 2024).
pancreatitis (2 papers, 2006 to 2014). Inflammation of the pancreas. "In the antisense treated rats with pancreatitis there was 3.5-fold greater serum amylase, increased tissue edema and histological inflammatory scores, and elevated levels of IL-1α, IL-1β, and IL-4 mRNAs in peripheral blood monocytes compared to rats treated with a sense oligonucleotide." (PMID 16700916, 2006). "Indeed, we observed that induction of pancreatitis robustly increased plasma concentration of several inflammatory cytokines including IL1α (2.6-fold), IL1β (12.8-fold), VEGF (70.5-fold) TNFα (4.5-fold), and IL6 (585.2-fold) as well as stimulated p38 kinase activation in pancreatic tissue." (PMID 24480543, 2014).
pneumococcal meningitis (2 papers, 2013 to 2025). An acute purulent infection of the meninges and subarachnoid space caused by Streptococcus pneumoniae, most prevalent in children and adults over the age of 60. "Advanced age was associated with the presence of autoantibodies against IFN-ω (66 vs. 62 years, p = 0.02) and IL-1α (67 vs. 62 years, p = 0.03) among patients with pneumococcal meningitis." (PMID 41161094, 2025).
prediabetes (2 papers, 2018 to 2023). "Our findings showed that IL-1α, IL-1β and IL-2 were significantly elevated in individuals with prediabetes when compared with normal controls." (PMID 37457235, 2023). "The present finding showed that serum Interleukin IL-2, IL-1β, and IL-1α levels of all prediabetes patients were increased when compared with healthy control cases (P < 0.05)." (PMID 37457235, 2023). "In prediabetes cases levels of cytokines: IL-2, IL-1β, and IL-1α were observed to be significantly higher than control group." (PMID 37457235, 2023).
preeclampsia (2 papers, 2010 to 2017). Preeclampsia is a hypertensive disorder of pregnancy that is characterized by new-onset hypertension with proteinuria presenting after 20 weeks of gestation, and depending on mild or severe forms may initially present with severe headache, visual disturbances, and hyperreflexia. "Elevated circulating IL-1 receptor antagonist concentrations in preeclampsia reflect increased activity of the pro-inflammatory cytokines IL-1α and β, which have a very short half-life in the circulation, and therefore it is difficult to detect a difference in their serum levels." (PMID 21126355, 2010).
psoriatic arthritis (2 papers, 2018 to 2026). Joint inflammation associated with psoriasis. "Ninety pediatric participants (JIA, CD, psoriatic arthritis, healthy controls) underwent serum cytokine profiling (IL-1α, IL-1β, IL-36α, IL-37, IL-6, IL-18, IL-27, IL-31) at baseline and 12 months." (PMID 42196228, 2026).
pterygium (2 papers, 2021 to 2023). A wedge-shaped fibrovascular lesion arising from the bulbar conjunctiva and extending to the cornea. "The dichloromethane extract of S. dendroideum promoted corneal healing in a murine model of pterygium-like eye lesions and exhibited immunomodulatory effects by reducing the levels of pro-inflammatory cytokines TNF-α and IL-1α, maintaining the expression of the anti-inflammatory cytokine IL-10." (PMID 37895904, 2023).
Pulmonary hemorrhage (2 papers, 2016 to 2026). Pulmonary hemorrhage is a bleeding within the lungs. "In 4T1 models, B. lactis V9 co-therapy mitigated αPD-1-induced uterine inflammation and pulmonary hemorrhage by downregulating IL-1α, IL-1β, and IL-17A while maintaining effector cytokines." (PMID 42273689, 2026).
pulmonary TB (2 papers, 2020 to 2024). "Compared with pulmonary tuberculosis group, NSCLC patients showed more abundant IL1A in pleural effusion." (PMID 32047552, 2020).
radiation pneumonitis (2 papers, 2014 to 2020). Inflammation of the lung due to harmful effects of ionizing or non-ionizing radiation. "Furthermore, persistently elevated IL1a (interleukin 1 alpha) and IL6 (interleukin 6), ICAM 1 (intercellular adhesion molecule 1), SP-A (surfactant protein A) and SP-D (surfactant protein D) serum levels are predictive for the development of radiation pneumonitis." (PMID 33521012, 2020).
Respiratory tract infection (2 papers, 2017 to 2019). An infection of the upper or lower respiratory tract. "During respiratory tract infections, the early expression of IL-1α by CCR2+ monocytes precedes the recruitment of neutrophils to the lung." (PMID 31425553, 2019).
retinal degeneration (2 papers, 2018 to 2023). Degeneration of the retina. "There is a strong correlation between DIM-conserved markers in the brain and the proinflammatory molecules known to be cytotoxic in retinal degeneration, including Il-1α, Il-1β, Tnf-α, and Tlr4, as well as NO and ROS production." (PMID 36779012, 2023). "In P23H model of retinal degeneration, an increased expression of Tnf-α, Il-1α, and Il-1β could, at least in part, explain the increased loss of photoreceptors observed in LPS-injected P23H rats." (PMID 29500424, 2018).
Rickettsia infection (2 papers, 2012 to 2022). "Adoptive transfer experiments identified that IL-1α secretion by macrophages was critical for controlling rickettsiosis in WT mice." (PMID 35130729, 2022). "Antirickettsial activity of IL-1α is involved in restricting Rickettsia infection." (PMID 35130729, 2022). "in vivo, IL-1α or IL-1β function was neutralized via tail vein (intravenous [i.v.]) injection with anti-IL-1α, anti-IL-1β, or anti-IgG-isotype control antibodies (Abs) into C57BL/6J WT mice in our established model of mild rickettsiosis (LD25; ∼105 PFU)." (PMID 35130729, 2022). "IL-1α is not detectable in the blood of acute BF patients, probably because stimulation of ECs causes the production of IL-1α predominantly in a cell-associated form, thus contributing to the localized procoagulant and inflammatory responses which occur during rickettsial disease." (PMID 21912565, 2012).
Rotavirus infection (2 papers, 2020 to 2021). Infection with any of the rotaviruses. "In rotavirus infection, ILC3 responds to IL-1α secreted from intestinal epithelial cells." (PMID 34079535, 2021).
sarcoidosis (2 papers, 2022 to 2023). Sarcoidosis is a multisystemic disorder of unknown cause characterized by the formation of immune granulomas in involved organs. "In sarcoidosis, a IL-1a SNP was significantly overrepresented in sarcoidosis subjects (compared to controls)." (PMID 36388923, 2022). "Enriched genes including MPO (myeloperoxidase), CXCL11, IL1A, CXCL10, FCGR3B, IL1B, TTN (titin), BATF2, VIP (vasoactive intestinal peptide), TLR3, CCR2, TLR7, and CR1 wereclosely related to sarcoidosis." (PMID 38137330, 2023).
schistosomiasis (2 papers, 2019 to 2023). An infectious disease caused by parasitic trematodes of the genus Schistosoma that colonize human blood vessels and release eggs that can cause granulomatous reactions leading to acute (swimmer's itch or acute schistosomiasis syndrome) or chronic disease. "Schistosomiasis treatment induces a profound reduction of HIV entry into cervical and blood CD4+ T cells that is sustained for up to two months, despite transient systemic and mucosal immune activation and elevated genital IL-1α levels." (PMID 31127086, 2019).
silicosis (2 papers, 2015 to 2025). Silicosis is a respiratory disease caused by breathing in (inhaling) silica dust. "Therefore, we performed this meta-analysis to precisely evaluate the association between the IL-1α +4845G/T, IL-1β +3953C/T, IL-1RA +2018T/C, IL-1β -511C/T, IL-6 -634C/G, IL-6 -174G/C, and IL-17A -832A/G polymorphisms and silicosis susceptibility." (PMID 40182855, 2025).
spinal cord injury (2 papers, 2024 to 2025). Penetrating and non-penetrating injuries to the spinal cord resulting from traumatic external forces (e.g., WOUNDS, GUNSHOT; WHIPLASH INJURIES; etc.). "Recent studies have reported that IL1A can rapidly induce neutrophil infiltration in rats with spinal cord injury (SCI)." (PMID 40612864, 2025).
Still’s disease (2 papers, 2021 to 2023). "The preferential endothelial activation of KD compared to Still’s disease is strongly enhanced by the release of interleukin 1 alpha and the direct toxicity of the IgA toward the endothelial cells." (PMID 34362028, 2021).
streptococcal infection (2 papers, 2015 to 2024). Any of the several infectious disorders caused by members of streptococcus, a genus of gram positive bacteria belonging to the family Streptococcaceae. "In a mouse model of sub-cutaneous Streptococcus infection, IL-1α was shown to induce unique transcriptomic changes to the liver, whilst IL-1β had more effect on the spleen transcriptome." (PMID 39127259, 2024). "IL-1α probably plays at most a minor role during streptococcal infections, as IL-1β−/− mice phenocopy IL-1R−/− mice in their resistance to GBS." (PMID 26500655, 2015).
thyroid (2 papers, 2020). "In concordance, IL-1α, produced by activated immune, epithelial and endothelial cells in response to cell injury and apoptosis, is considered an apoptosis index of the target cell and proportional to the degree of lymphoid infiltration in thyroid disorders." (PMID 32182948, 2020).
tongue SCC (2 papers, 2015 to 2020). "In one study, salivary levels of IL-1α, IL-6, IL-8, vascular endothelial growth factor A (VEGF-a) and TNF-α were able to predict the progression of tongue SCC from high-risk to neoplasm, serving as potential biomarkers for cancer screening and early detection." (PMID 26082902, 2015).
toxoplasmosis (2 papers, 2020 to 2022). A parasitic disease contracted by the ingestion or fetal transmission of toxoplasma gondii. "It is also surprising that the observed increase of IL-1α expression, a pro-inflammatory cytokine-related protection against toxoplasmosis that drastically reduces parasite growth, found in OvMØs infected with PRU II isolates, was otherwise associated with a M2 profile." (PMID 36552372, 2022). "TNF-α and IL-1α are critical for survival during acute murine toxoplasmosis." (PMID 32733463, 2020). "However, the role of IL-1α cytokines during T. gondii infection is not yet fully understood, as they have been shown to participate in the protection against toxoplasmosis in murine models but also to play no role or even to be counterproductive and favor the advance of the disease." (PMID 36552372, 2022).
Tracheomalacia (2 papers, 2019 to 2021). "The expression of cytokines, IL-8, IL17A, and IL-1α, is higher in patients affected by tracheomalacia, and this has the potential to indicate the presence of chronic airway inflammation and also lung microbiota disequilibrium, with a prevalence of Pseudomonas at the BALF." (PMID 34356592, 2021).
Ureteral obstruction (2 papers, 2019 to 2023). Obstruction of the flow of urine through the ureter. "Unilateral ureteral obstruction (UUO) in the neonatal mouse caused renal structural injury, induced key molecules of the necrosome (RIPK3 and phospho-MLKL) and generated inflammatory cytokines (IL-1α, INF-γ and TNF-α) in the neonatal kidney." (PMID 31819111, 2019). "mRNA expression of IL1α, IL1β and IL18 but not of TNFα increased in response to ureteral obstruction (D and C correspondingly)." (PMID 37553369, 2023).
urothelial carcinoma (2 papers, 2021 to 2025). A malignant neoplasm derived from the transitional epithelium of the urinary tract (urinary bladder, ureter, urethra, or renal pelvis). "Our results demonstrate that mouse Apobec3 and human APOBEC3A promote squamous differentiation in urothelial carcinoma and that this trans-differentiation phenotype is mediated through IL-1α signaling, a target of FDA approved therapies for rheumatologic disease." (PMID 41390483, 2025).
/T-cell lymphomas (1 paper, 2012). "The up-regulation of IL1A was previously shown in EBV-positive NK/T-cell lymphomas along with mRNAs of other genes thought to be involved in cell proliferation such as BCL6 or ERBB4." (PMID 22870299, 2012). "A previous study had determined the mRNA expression profile of EBV-infected nasal NK/T-cell lymphoma lines and found, among others, the IL1A, BCL6, CD44 and c-FOS genes to be induced and the interleukin 1 receptor 1 (IL1R1) gene to be repressed compared to normal lymphocytes." (PMID 22870299, 2012).
acute chest syndrome (1 paper, 2024). A vaso-occlusive crisis of the pulmonary vasculature occurring in patients with sickle cell disease. "Numerous cytokines elevated in our study, such as IL-1α, IL-4, IL-5,IL-6, IL-7, IL-8, TNF-α were previously shown to involved in VOC-related acute clinical complications such as acute chest syndrome, pulmonary hypertension, and pulmonary thrombosis." (PMID 38361924, 2024).
acute esophagitis (1 paper, 2022). "The interleukin 1 (IL1) family pathway with its downstream effectors (IL1A, IL1R1, IL1RN, IL1B) are esophagus-specific genes and were shown in previous studies to be linked, among others, with the development and progression of acute esophagitis and BE." (PMID 35328735, 2022).
acute GVHD (1 paper, 2025). "Our study identified the donor IL-1α rs1800587 CC/CT genotype as a possible genetic risk factor for developing moderate to severe acute GVHD (grade II - IV) in pediatric patients who underwent allogeneic HSCT." (PMID 41291248, 2025). "The results of the multivariate analysis revealed a hazard ratio of 0.17 (confidence interval 0.0229-1.27), and a trend that IL-1α rs1800587 could be an independent risk factor for acute GVHD (p = 0.084)." (PMID 41291248, 2025). "Our multivariate analysis indicated a trend, suggesting that the IL-1α rs1800587 CC/CT genotype might be an independent risk factor for developing acute GVHD." (PMID 41291248, 2025). "Our analyses have shown that patients who receive cells from a donor with the CC or CT genotype of the IL-1α rs1800587 SNP have a higher rate of acute GVHD (grade II to IV)." (PMID 41291248, 2025). "We performed a multivariate analysis to assess the potential independent influence of the IL-1α rs1800587 factor on the incidence of acute GVHD after HSCT." (PMID 41291248, 2025). "Other analyses involving siblings or unrelated donors did not yield any significant results, indicating that the IL-1α rs1800587 SNP causes a higher incidence of acute GVHD." (PMID 41291248, 2025). "To analyze an association between the genotypes IL-1α rs1800587, IL-1β rs16944, and IL-1β rs1143627 of recipients and donors and the occurrence of acute GVHD, we compared those who experienced clinically significant acute GVHD." (PMID 41291248, 2025). "We observed a trend (p = 0.084), suggesting that the CC/CT genotype of IL-1α rs1800587 might be an independent factor for developing acute GVHD." (PMID 41291248, 2025).
acute liver failure (1 paper, 2025). Rapid deterioration of liver function causing encephalopathy and coagulopathy. "In vivo studies in different acute liver failure (ALF) animal models have shown the existence of cell death by necrosis resulted in rapid IL-1α precursor release and upregulation of IL-1β and IL-18, leading to tissue injury with massive upregulation of anti-inflammatory molecule IL-1Ra." (PMID 40529491, 2025).
acute monocytic leukemia (1 paper, 2025). Acute monoblastic leukemia (AML-M5), is one of the most common subtypes of acute myeloid leukemia (AML) that is either comprised of more than 80% of monoblasts (AML-M5a) or 30-80% monoblasts with (pro)monocytic differentiation (AML-M5b). "According to pre-clinical research, after silencing PCSK9 expression with siRNA, significant reduced IL-1α, IL-6, and TNF-α expression, as well as downregulated activation of the NF-κB pathway, were observed in human THP-1 (an acute monocytic leukemia cell line) cells." (PMID 40872487, 2025).
adult T cell leukemia (1 paper, 2017). "Previous studies have shown that IL-1α can be constitutively produced by adult T cell leukemia and was considered as an autocrine growth factor for ALL." (PMID 28152513, 2017).
aggressive periodontitis (1 paper, 2014). "A number of published studies investigated the association between interleukin-1α (IL-1α) −899 (+4845) C→T polymorphism and susceptibility to aggressive periodontitis (AgP)." (PMID 24748978, 2014).
alcohol liver disease (1 paper, 2015). "Additionally, polymorphisms in the genes encoding the IL-1R antagonist (IL-1ra; Il1rn) and IL-1β (Il1b), but not IL-1α (Il1a) and IL1-R1 (IL-1R1 type 1; Il1r), have been associated with a susceptibility to alcoholism or ALD (alcohol liver disease) in Spanish men." (PMID 25852553, 2015).
allergic conjunctivitis (1 paper, 2017). "To confirm our in vivo results, we used a separate in vitro model consisting of IL-1α-pretreated conjunctival epithelial cells, which we found to show an inflammatory response similar to that in allergic conjunctivitis." (PMID 28046113, 2017). "This suggests that IL-1α-pretreated conjunctival epithelial cells could act as a substitute in vitro model of the in vivo mouse model of OVA-induced allergic conjunctivitis in terms of the response of inflammatory cytokines." (PMID 28046113, 2017). "Thus, cells treated with IL-1α could act as a substitute for the in vivo mouse model of EAC in terms of the inflammatory response, even though they do not exhibit the pathology of allergic conjunctivitis." (PMID 28046113, 2017).
alopecia totalis (1 paper, 2023). Alopecia totalis is a form of alopecia areata, an inflammatory disease of the hair follicle, characterized by a complete loss of hair of the entire scalp which becomes glabrous. "Polymorphisms in the IL‐1RA gene/‐s have been linked to an increased predisposition to the more severe forms of AA; alopecia totalis and universalis, indicating a reduced ability to control IL‐1α and IL‐1β signalling." (PMID 37275428, 2023).
amyloidosis (1 paper, 2021). A disorder characterized by the localized or diffuse accumulation of amyloid protein in various anatomic sites. "In the current model, we focused on the prevention of gastrointestinal amyloidosis using neutralizing antibodies against inflammatory cytokines TNF-α and IL-1α/β; however, amyloidosis was partially ameliorated in both groups." (PMID 35008464, 2021). "KCASP1Tg mice were treated with neutralizing antibodies against TNF-α or IL-1α/β to prevent gastrointestinal amyloidosis, and amyloidosis was partially ameliorated." (PMID 35008464, 2021).
anaerobic bacterial infections (1 paper, 2017). "In the context of anaerobic bacterial infections, mRNA expression of IL1α, CXCL8, TNFα and human beta defensin (hBD)-2 were stimulated in keratinocytes by Propionibacterium acnes, an anaerobic bacterium." (PMID 28959685, 2017).
anaphylaxis (1 paper, 2011). An acute hypersensitivity reaction that occurs from exposure to an allergen. "In addition to parenchymal cells, several IL-1α-positive cells were observed perivascularly around dilated blood vessels after anaphylaxis, indicating that IL-1α expression may be associated with the development of vasogenic oedema." (PMID 22114895, 2011). "In contrast, high numbers of IL-1α-immunopositive and IL-1β mRNA expressing cells and dilated blood vessels were seen in the brain after anaphylaxis and MCAo, which indicates that these changes were initiated in response to systemic inflammatory challenge." (PMID 22114895, 2011).